NEPNP (nephrocan, pseudogene)
Synonyms: NPN; NEPN
Gene: Unitary pseudogene on chromosome 6 (117,633,706 to 117,645,087, forward strand). Ensembl gene ENSG00000218233.
Diseases named in the same sentence as NEPNP in open-access papers:
NEPNP is named in the same sentence as 2 diseases in open-access papers, as found by Europe PMC text mining. Sharing a sentence is not in itself a finding about the gene and the disease.
NEPNP shares sentences with these, for which no sentence is quoted: breast carcinoma (1 paper); breast tumor (1).